CDK5 (cyclin dependent kinase 5)
Diseases named in the same sentence as CDK5 in open-access papers (continued):
Sharing a sentence is not in itself a finding about the gene and the disease.
cyst (1 paper, 2021). A sac-like closed membranous structure that may be empty or contain fluid or amorphous material. "Another study in jck/Nek8/Nphp9 mice demonstrated that roscovitine ameliorated the elongated cilia phenotype and restored tubular epithelial differentiation, while conditional inactivation of CDK5 reduced cilia length, total kidney volume and cyst formation." (PMID 34055783, 2021).
delirium (1 paper, 2025). A disorder characterized by confusion; inattentiveness; disorientation; illusions; hallucinations; agitation; and in some instances autonomic nervous system overactivity. "While it is clear that the hypothalamic-pituitary-adrenal axis plays a role in the maintenance of sleep/wake patterns, there is some evidence to link sleep cycle disturbance with systemic infections and delirium through the influence of CDK5 gene expression in the hypothalamus." (PMID 40171450, 2025).
demyelination (1 paper, 2018). "These higher expressions of MAG, MBP, and CDK5 in TG mice increase protecting adaption, thus decrease the sensitivity to METH-induced demyelination." (PMID 29467717, 2018).
Dyskinesia (1 paper, 2023). A movement disorder which consists of effects including diminished voluntary movements and the presence of involuntary movements. "In conclusion, our study identified BK channels in striatal cholinergic neurons as new targets for CDK5 phosphorylation, and we described electrophysiological and molecular mechanisms of Cdk5-deficiency-mediated dyskinesia-like behaviors." (PMID 37223477, 2023). "Restoration of CDK5 expression in striatal cholinergic neurons reduced dyskinesia-like behaviors in ChAT-Cre;Cdk5f/f mice." (PMID 37223477, 2023). "The therapeutic relevance of our findings is highlighted by the amelioration of dyskinesia-like behaviors after local restoration of CDK5 in ChAT-Cre;Cdk5f/f mice." (PMID 37223477, 2023). "In future, it would be interesting to further explore whether CDK5-induced phosphorylation of BK channels also involves in dyskinesia-like behaviors of other neurological diseases." (PMID 37223477, 2023). "In addition, we demonstrated that restoration of CDK5 expression in striatal cholinergic neurons ameliorated cholinergic-neuron Cdk5-deficit-triggered dyskinesia-like behaviors." (PMID 37223477, 2023). "Together, these findings indicate that CDK5-induced phosphorylation of BK channels involves in cholinergic-neuron-mediated motor function, providing a potential new therapeutic target for treating dyskinesia-like behaviors arising from neurological diseases." (PMID 37223477, 2023). "In contexts where high BK current densities in striatal cholinergic neurons are associated with hyperexcitability of cholinergic neurons, the novel CDK5 activator may provide an intervention target to suppress dyskinesia-like behaviors in neurological disorders." (PMID 37223477, 2023).
endotoxemia (1 paper, 2021). "Genetic deletion of Cdk5 in myeloid cells increases c-Maf and hence Il-10 levels during LPS-induced endotoxemia, contributing to reduced lung inflammation and increased survival." (PMID 34502552, 2021). "In this study, we investigated whether the deletion of Cdk5 in macrophages regulates Il-10 production through c-Maf during LPS-induced endotoxemia." (PMID 34502552, 2021). "Together, these results suggest that the deletion of Cdk5 in macrophages increases c-Maf expression in the lung tissue and thus induces the expression of the anti-inflammatory cytokine Il-10 during LPS-induced endotoxemia." (PMID 34502552, 2021). "In summary, our data reveal a previously unknown role of Cdk5 in myeloid cells in the regulation of inflammatory processes during LPS-induced endotoxemia." (PMID 34502552, 2021). "Next, we wanted to examine whether myeloid-specific deletion of Cdk5 in mice exposed to LPS-induced endotoxemia would enhance systemic plasma Il-10 levels and contribute to increased survival." (PMID 34502552, 2021). "Therefore, our aim was to investigate whether Cdk5 deletion in myeloid cells modulates Il-10 production during endotoxemia." (PMID 34502552, 2021). "Mice lacking Cdk5 in macrophages (Cdk5LysMcre) show increased pulmonary c-Maf, Il-10, and plasma Il-10 levels in a model of LPS-induced endotoxemia, resulting in improved disease severity and survival." (PMID 34502552, 2021). "In an in vivo mouse model of LPS-induced endotoxemia, mice lacking Cdk5 in macrophages showed increased levels of c-Maf and elevated levels of Il-10 in lungs as well as in plasma, resulting in ameliorated survival." (PMID 34502552, 2021).
esophageal adenocarcinoma (1 paper, 2025). A malignant tumor with glandular differentiation arising predominantly from Barrett mucosa in the lower third of the esophagus. "Interestingly, the TCGA database showed that LIMK1 and CDK5 mRNA expression was not only significantly upregulated in ESCC but also in esophageal adenocarcinoma (EAC), another pathological subtype of esophageal cancer prevalent in Western counties." (PMID 40476449, 2025).
esophageal cancer (1 paper, 2025). A primary or metastatic malignant neoplasm involving the esophagus. "Their study demonstrates that LIM domain kinase 1 (LIMK1) and Cyclin‐dependent kinase 5 (CDK5) synergistically increase the phosphorylation of β‐catenin, thereby activating the Wnt/β‐catenin signaling pathway to promote esophageal cancer metastasis." (PMID 40476449, 2025). "Correlation between CDK5 expression levels and clinicopathological parameters in 208 patients with esophageal cancer." (PMID 40476449, 2025). "In addition, the datasets from TCGA also indicated that LIMK1 and CDK5 mRNA expression were significantly upregulated in esophagus cancer patients." (PMID 40476449, 2025). "Furthermore, the authors propose a therapeutic strategy targeting esophageal cancer metastasis using combination therapy with LIMK1 and CDK5 inhibitors." (PMID 40476449, 2025).
gastric tumor (1 paper, 2023). "Our findings demonstrate that CDK5 promotes gastric tumor cell apoptosis by directly binding to and stabilizing DP1 and activating E2F1 signaling." (PMID 37990321, 2023). "Using western blotting, we examined CDK5 protein levels in frozen gastric tumor tissues collected from 19 patients who received neoadjuvant chemotherapy." (PMID 37990321, 2023). "Clinicopathological analysis indicated that CDK5 depletion correlated with poor prognosis and chemoresistance in human gastric tumors." (PMID 37990321, 2023). "Moreover, western blotting confirmed that overexpression of CDK5 activated the intrinsic apoptotic pathway, as indicated by the increased levels of cleaved PARP and caspase 3, which possibly contributed to the inhibition of gastric tumor growth." (PMID 37990321, 2023).
glomerular disease (1 paper, 2021). "We next assessed the biological impact of podocyte Cdk5 deficiency in glomerular disease." (PMID 34572114, 2021). "Experimental glomerular disease was induced after doxycycline-dependent Cdk5 knockout by intraperitoneal injection of nephrotoxic serum (NTS) in mice 10 weeks of age." (PMID 34572114, 2021). "In the present study, conditional and inducible knockout models of Cdk5 were analyzed to investigate the role of Cdk5 in podocyte development and glomerular disease." (PMID 34572114, 2021). "In glomerular disease, signaling mechanisms via Cdk5 have been addressed by single or combined conventional knockout of known specific activators of Cdk5." (PMID 34572114, 2021). "In addition, we delineated the contribution of Cdk5 in states of glomerular disease, employing inducible podocyte-specific Cdk5 knockout mice and the NTN disease model." (PMID 34572114, 2021). "In summary, Cdk5 acts primarily as master regulator of podocyte survival during glomerular disease and—in contrast to neurons—does not impact on glomerular development or maintenance." (PMID 34572114, 2021).
graft versus host disease (1 paper, 2020). An immune system disorder that occurs after allogeneic hematopoietic stem cell transplant and is a reaction of donor immune cells against host tissues. "Furthermore, transplantation of Cdk5-null bone marrow stem cells and T cells, derived from C57BL/6 J mice into lethally irradiated B6D2F1 mice, resulted in a significant reduction in graft-versus-host disease (GVHD)." (PMID 31910742, 2020).
hematoma (1 paper, 2022). A hematoma is a collection of blood from a vascular structure into an extravascular space. "Compared with the sham operation group, the number of CDK5 positive cells near the hematoma in the ICH group increased." (PMID 35795154, 2022).
HIV encephalitis (1 paper, 2011). "CDK5-mediated CRMP2 phosphorylation was significantly increased in the hippocampus of patients with HIV encephalitis and in gp120 transgenic mice, and this effect was rescued by genetic down-modulation of CDK5 in the mouse model." (PMID 21943307, 2011).
Hypercalcemia (1 paper, 2022). An abnormally increased calcium concentration in the blood. "It is possible that hypercalcemia may induce the expression of Drp1 and Fis1 by regulating key factors such as CaMKII, PP2A regulatory subunit Bβ2, CDK5, and calcineurin, which shall be excavated in the following experiments." (PMID 36050772, 2022).
hypoadiponectinemia (1 paper, 2020). "Although CDK5 inhibitors have the potential to improve metabolic conditions associated with hypoadiponectinemia, the effects of CDK5 inhibitors on adiponectin biosynthesis has not been fully investigated." (PMID 32054125, 2020).
inflammatory bone disorders (1 paper, 2022). "However, further studies are necessary to elucidate the role of Cdk5 in bone, particularly in inflammatory bone disorders." (PMID 35203613, 2022).
injury (1 paper, 2023). Damage inflicted on the body as the direct or indirect result of an external force, with or without disruption of structural continuity. "However, to our knowledge, no papers have been published about CDK5 associated with BPD brain injury." (PMID 36964998, 2023).
insulinoma (1 paper, 2019). "In mouse insulinoma (MIN6) cells, a specific inhibitor of CDK5 raised insulin secretion." (PMID 31822470, 2019).
intracerebral hemorrhage (1 paper, 2022). A cerebrovascular disorder characterized by bleeding into one or both cerebral hemispheres including the basal ganglia and the cerebral cortex. "Inhibition of Cdk5 activity, such as knockout of Cdk5 kinase activity or glycosylated Cdk5, also showed neuroprotective effect in intracerebral hemorrhage." (PMID 35966199, 2022). "Therefore, Cdk5 plays an important role in intracerebral hemorrhage and is a potential therapeutic target." (PMID 35966199, 2022).
invasive breast carcinoma (1 paper, 2020). A carcinoma that infiltrates the breast parenchyma. "We sought to determine the frequency of Cdk5 overexpression in a large cohort of early‐stage invasive breast cancers to determine whether Cdk5 expression was associated with poor patient survival and test associations with clinicopathological criteria." (PMID 32352232, 2020).
kidney cancer (1 paper, 2019). Primary or metastatic malignant neoplasm involving the kidney. "To date, the research of CDK5 in kidney cancer still limited, and our study focused on the expression of CDK5 in ccRCC patients, which is the most common pathological type." (PMID 31311512, 2019). "The data from both of The Cancer Genome Atlas (TCGA) and Gene Expression of Normal and Tumor Tissue (GENT) were analyzed for determining the expression of CDK5 in kidney cancer." (PMID 31311512, 2019). "Firstly we compared the CDK5 mRNA expression in kidney cancer from both TCGA and GENT databases." (PMID 31311512, 2019). "The CDK5 expression was significantly lower in cancer tissue compared with normal in TCGA (p < 0.0001), GENT database also showed a relative low expression in kidney cancer." (PMID 31311512, 2019).
Lewis lung carcinoma (1 paper, 2016). "Finally, we assessed the effect of anti-VEGF treatment on Lewis lung carcinoma (LLC) growth in endothelial-specific Cdk5 knockout mice." (PMID 26755662, 2016).
Lewy body disease (1 paper, 2018). "Further, the application of CDK5 in cortex suffering from Lewy body disease was reported in 2000, indicating that CDK5 may participate in the formation of Lewy bodies." (PMID 30333786, 2018).
lymphedema (1 paper, 2015). Excess fluid collection in tissues, causing swelling. "Endothelial-specific deletion of Cdk5 causes congenital lymphatic dysfunction with lymphedema and finally results in embryonic lethality." (PMID 26327394, 2015). "Deletion of Cdk5 in the mouse endothelium results in severe lymphedema formation and embryonic lethality." (PMID 26327394, 2015).
mesothelioma (1 paper, 2025). A usually malignant and aggressive neoplasm of the mesothelium which is often associated with exposure to asbestos. "Moreover, guadecitabine specifically activated in CIMP PM cells the CDK5 signaling, involved in the inhibition of cell migration, and Sphingosine-1-phosphate Signaling that inhibited the growth of mesothelioma cell lines and induced cell cycle arrest at the G0/G1." (PMID 39966970, 2025).
metastasis (1 paper, 2015). The spread or migration of cancer cells from one part of the body (where they first appeared) to another. "The expression of miR-21 and CDK5 were significantly correlated with lymph node metastasis in HNSCC." (PMID 26690371, 2015).
motor neuron disease (1 paper, 2020). "Oxidative stress is reported not only to induce the translocation of Cdk5 from cytoplasm to the nucleus, which could alter its substrate specificity, but also to increase the Cdk5 activity in experimental motor neuron disease." (PMID 33291667, 2020).
myelodysplastic syndrome (1 paper, 2022). A clonal hematopoietic disorder characterized by dysplasia and ineffective hematopoiesis in one or more of the hematopoietic cell lines. "In the human genome, CDK5 is localized on the long arm of chromosome 7 that is recurrently deleted in AML and myelodysplastic syndrome (MDS) and is associated with poor prognosis." (PMID 35514210, 2022).
myeloid malignancies (1 paper, 2022). "As loss of chromosome 7 (−7/7q) that encodes CDK5 is a poor prognostic marker in myeloid malignancies, our results open the door to prioritize clinical evaluation of DHODHi in a challenging patient population for which there are currently limited therapeutic options." (PMID 35514210, 2022).
neuralgia (1 paper, 2022). "Researchers have visualized the regulation of trigeminal sensory neurons by Cdk5, showed the expression change of Cdk5 and the accumulation of calcium ions, and provided a strong basis for revealing the pathological mechanism of neuralgia." (PMID 35966199, 2022).
neuropathic pain (1 paper, 2019). Chronic pain caused by damage to nerve fibers. "Considering this, a positive feedback mechanism of upregulated SUMOylation increasing Cdk5 activity, resulting in increased CRMP2 phosphorylation and facilitation of subsequent CRMP2 SUMOylation could contribute to neuropathic pain." (PMID 31080913, 2019).
osteoporosis (1 paper, 2022). A condition of reduced bone mass, with decreased cortical thickness and a decrease in the number and size of the trabeculae of cancellous bone (but normal chemical composition), resulting in increased fracture incidence. "We conclude that Cdk5 is a potential therapeutic target to treat osteoporosis and improve fracture healing." (PMID 35383146, 2022). "Therefore, our findings suggest that targeting Cdk5 could serve as a therapeutic approach to treat osteoporosis." (PMID 35383146, 2022).
pheochromocytoma (1 paper, 2021). "Furthermore, our previous study reported that neurotrophic growth factors such as nerve growth factor induce neuronal differentiation in rat pheochromocytoma cells through ERK and EGR1 activation, associated with p35/CDK5 activation." (PMID 34207842, 2021).
polycystic kidney disease (1 paper, 2022). A usually autosomal dominant and less frequently autosomal recessive genetic disorder characterized by the presence of numerous cysts in the kidneys leading to end-stage renal failure. "Reducing ciliary body length by drug or gene inhibition of CDK5 can reduce polycystic kidney disease in renal tuberculosis model." (PMID 35874807, 2022).
preeclampsia (1 paper, 2022). Preeclampsia is a hypertensive disorder of pregnancy that is characterized by new-onset hypertension with proteinuria presenting after 20 weeks of gestation, and depending on mild or severe forms may initially present with severe headache, visual disturbances, and hyperreflexia. "The highest observed to expected ratio value was seen for CDK5RAP2, a regulator of CDK5 (cyclin-dependent kinase 5) activity, which is implicated in preeclampsia via the regulation of Nestin, a cytoskeleton protein expressed in podocytes that serve as barriers to protein leakage." (PMID 35860693, 2022).
rhabdomyosarcoma (1 paper, 2018). A rare aggressive malignant mesenchymal neoplasm arising from skeletal muscle. "Furthermore, disrupting Cdk5 in rhabdomyosarcoma also led to IFN-γ-induced PD-L1 ineffectiveness, supporting a general role of Cdk5 in PD-L1 regulation in cancer cells." (PMID 30687086, 2018).
salivary gland cancer (1 paper, 2021). A primary or metastatic malignant neoplasm that affects the major or minor salivary glands. "Further, using CDK5 siRNA, we show that salivary gland cancer cell lines are sensitive to inhibition of CDK5 as a function of LMW-E expression, but independent of CDK2 status." (PMID 33990543, 2021).
selenium deficiency (1 paper, 2022). A nutritional deficiency disease resulting from inadequate selenium levels in the body, which can lead to impaired function of selenoproteins essential for antioxidant defense and thyroid hormone metabolism. "In addition to selenium deficiency, T-2 toxin can also increase the mRNA expression of CDK5." (PMID 36588792, 2022).
serous carcinomas (1 paper, 2020). "Expression levels of DARPP‐32, PP1 and Cdk5 were assessed in the high‐grade serous carcinoma histological subtype." (PMID 32588513, 2020).
temporal lobe epilepsy (1 paper, 2020). A localization-related (focal) form of epilepsy characterized by recurrent seizures that arise from foci within the temporal lobe, most commonly from its mesial aspect. "Similarly, CDK5 and GSK-3β were both reported to be overactivated in temporal lobe epilepsy." (PMID 33681188, 2020).
testis cancer (1 paper, 2024). "Nevertheless, protein expression data show that 9 of 12 patients with testis cancer show high/medium expression of CDK5 (Human Protein Atlas, proteinatlas.org, accessed on 12 January 2024)." (PMID 38474332, 2024). "CDK5 is reported as not prognostic in testis cancer, and the expression of its RNA indicates low cancer specificity." (PMID 38474332, 2024).
Timothy syndrome (1 paper, 2021). "Suppressing CDK5 activity also alleviates the cardiac phenotype associated with Timothy Syndrome." (PMID 34379189, 2021).
ZIKV infection (1 paper, 2020). "The CDK5 signaling pathway was predicted to be inhibited in the presence of the activation of ATM after ZIKV infection." (PMID 32708879, 2020).